MIR3179-1 (microRNA 3179-1)
Synonyms: hsa-mir-3179-1
Gene: MicroRNA gene on chromosome 16 (14,901,508 to 14,901,591, forward strand). Ensembl gene ENSG00000284305.
Gene Ontology:
Biological process: miRNA-mediated post-transcriptional gene silencing
Cellular component: RISC complex
Homologues: Paralogues in human: MIR3179-2 (100% identical), MIR3179-3 (100% identical), MIR3179-4 (100% identical).